LIN28A (lin-28 RNA binding posttranscriptional regulator A)
Description:
RNA-binding protein that inhibits processing of pre-let-7 miRNAs and regulates translation of mRNAs that control developmental timing, pluripotency and metabolism. Seems to recognize a common structural G-quartet (G4) feature in its miRNA and mRNA targets (Probable). 'Translational enhancer' that drives specific mRNAs to polysomes and increases the efficiency of protein synthesis. Its association with the translational machinery and target mRNAs results in an increased number of initiation events per molecule of mRNA and, indirectly, in mRNA stabilization. Binds IGF2 mRNA, MYOD1 mRNA, ARBP/36B4 ribosomal protein mRNA and its own mRNA. Essential for skeletal muscle differentiation program through the translational up-regulation of IGF2 expression. Suppressor of microRNA (miRNA) biogenesis, including that of let-7, miR107, miR-143 and miR-200c. Specifically binds the miRNA precursors (pre-miRNAs), recognizing an 5'-GGAG-3' motif found in pre-miRNA terminal loop, and recruits TUT4 and TUT7 uridylyltransferases. This results in the terminal uridylation of target pre-miRNAs. Uridylated pre-miRNAs fail to be processed by Dicer and undergo degradation. The repression of let-7 expression is required for normal development and contributes to maintain the pluripotent state by preventing let-7-mediated differentiation of embryonic stem cells. Localized to the periendoplasmic reticulum area, binds to a large number of spliced mRNAs and inhibits the translation of mRNAs destined for the ER, reducing the synthesis of transmembrane proteins, ER or Golgi lumen proteins, and secretory proteins. Binds to and enhances the translation of mRNAs for several metabolic enzymes, such as PFKP, PDHA1 or SDHA, increasing glycolysis and oxidative phosphorylation. Which, with the let-7 repression may enhance tissue repair in adult tissue (By similarity).
Synonyms: Lin-28A; CSDD1; LIN28; ZCCHC1; LIN-28; FLJ12457
Tractability: PROTAC: ubiquitination databases record sites on it; a small molecule that binds it is known.
Gene: Protein-coding gene on chromosome 1 (26,410,817 to 26,429,728, forward strand). Ensembl gene ENSG00000131914.
Subcellular location: Cytoplasm; Rough endoplasmic reticulum; Cytoplasm, P-body; Cytoplasm, Stress granule; Nucleus, nucleolus
Subcellular location (Human Protein Atlas): Cytosol; Nucleoli; Rods & Rings
Pathways (Reactome):
Developmental Biology: Transcriptional regulation of pluripotent stem cells
Gene Ontology:
Molecular function: mRNA binding; pre-miRNA binding; protein binding; protein-RNA adaptor activity; RNA binding; G-quadruplex RNA binding; miRNA binding; sequence-specific mRNA binding; nucleic acid binding; translation initiation factor binding; zinc ion binding
Biological process: miRNA catabolic process; negative regulation of pre-miRNA processing; positive regulation of cytoplasmic translation; pre-miRNA processing; RNA 3'-end processing; stem cell population maintenance; cellular response to glucose stimulus; negative regulation of translation; positive regulation of phosphatidylinositol 3-kinase/protein kinase B signal transduction; positive regulation of TOR signaling; positive regulation of cell proliferation involved in kidney development; post-transcriptional regulation of gene expression; stem cell differentiation
Cellular component: cytoplasm; cytoplasmic stress granule; cytosol; nucleus; P-body; rough endoplasmic reticulum; nucleolus
Genetic constraint (gnomAD): Loss-of-function variants: 11 observed, 21.9 expected, observed/expected ratio (o/e) 0.5, 90% interval 0.31 to 0.83. The upper end of that interval is the gene's LOEUF score, 0.83, which puts it in group 3 of 6, group 1 being the genes least tolerant of losing a copy. Missense variants: 219 observed, 292.77 expected, observed/expected ratio (o/e) 0.75, 90% interval 0.67 to 0.84. Synonymous variants: 111 observed, 113.86 expected, observed/expected ratio (o/e) 0.97, 90% interval 0.83 to 1.14.
Homologues: Orthologues: chimpanzee LIN28A (99% identical), rat Lin28a (98% identical), mouse Lin28a (97% identical), pig LIN28A (93% identical), tropical clawed frog lin28a (66% identical), zebrafish lin28aa (66% identical), zebrafish lin28ab (65% identical), Drosophila melanogaster lin-28 (36% identical), Caenorhabditis elegans cey-4 (23% identical), Caenorhabditis elegans cey-3 (19% identical), Caenorhabditis elegans cey-2 (19% identical). Paralogues in human: LIN28B (65% identical), YBX1 (36% identical), YBX2 (33% identical), YBX3 (29% identical).
Diseases named in the same sentence as LIN28A in open-access papers:
LIN28A is named in the same sentence as 152 diseases in open-access papers, as found by Europe PMC text mining. Sharing a sentence is not in itself a finding about the gene and the disease. The quoted sentences say what the papers report.
breast carcinoma (62 papers, 2011 to 2025). "Our findings underline a novel role for Lin28A in breast cancer development and activation of the AR axis." (PMID 27494865, 2016). "Similarly, the CSC phenotype in breast cancer cells was suppressed after the attenuation of Lin28A expression caused let-7b-dependent Wnt pathway inhibition." (PMID 36230562, 2022). "Of note, LIN28A was described to be regulated by the WNT pathway as a direct target of CTNNB, which results in increased LIN28A mRNA levels in breast cancer, adult mammalian retina, and mouse hippocampus and promotes proliferation." (PMID 40680886, 2025). "In breast cancer cells, a decrease in REST expression causes an increase in LIN28A, which induces an increase in cell proliferation." (PMID 38542313, 2024). "High levels of LIN28A (or LIN28B, the second Lin protein) are associated with many human cancers such as glioblastoma, ovarian, gastric, prostate and breast cancers, as well as pediatric cancers." (PMID 34445617, 2021). "LIN28A promoted cell proliferation and invasion and suppressed cell apoptosis in ER−/Her2+ breast cancer cells and accelerated breast cancer xenograft tumor growth in vivo by activating androgen receptor (AR) via recruiting c-myc to AR promoter region." (PMID 33381451, 2020). "In breast cancer, Wnt/β-catenin inhibits breast cancer stem cell expansion through direct binding to lin28a promoter and inhibits let-7a." (PMID 32650795, 2020). "In another study, LIN28A was reported to be responsible for breast cancer cell resistance to radiation." (PMID 28400788, 2017). "LIN28A was found to be upregulated in breast cancer and enhanced tumor growth and progression via regulation of c-myc signaling; LIN28A knockdown decreased tumor malignancy." (PMID 28587210, 2017). "In another study, depletion of LIN28A by shRNA reduced in vitro invasion ability of bone metastatic breast cancer cells." (PMID 28400788, 2017). "Taken together, these data demonstrated the functional importance of Lin28A and AR in human ER−/Her2+ breast cancer." (PMID 27494865, 2016). "Our study demonstrates that Lin28A can activates androgen receptor via regulation of c-myc and promotes malignancy of ER−/Her2+ breast cancer." (PMID 27494865, 2016). "In our study, overexpression of Lin28A introduced AR and c-myc expression, whereas knockdown of Lin28A inhibited AR and c-myc expression in ER-/Her2+ breast cancer cells." (PMID 27494865, 2016). "Overexpression of Lin28A inhibited let-7c expression, whereas knockdown of Lin28A increased let-7c expression in breast cancer cells." (PMID 27494865, 2016). "The expression of Lin28A and AR were examined after Lin28A siRNA and Lin28A plasmid were transfected into ER−/Her2+ breast cancer cells." (PMID 27494865, 2016). "Lin28A enhanced growth ability, colonies ability, cells proliferation activities, invasive ability and inhibited cells apoptosis of ER−/Her2+ breast cancer cells." (PMID 27494865, 2016). "We transfected Lin28A siRNA and Lin28A plasmid transiently into ER−/Her2+ breast cancer cells and found that increase of AR expression can enhances growth, invasion, and soft agar colony formation." (PMID 27494865, 2016). "The expression of Lin28A also promoted tumorigenicity of in nude mices which injected with ER−/Her2+ breast cancer cells." (PMID 27494865, 2016). "Further analysis showed a negative correlation between both onco-proteins, this result is similar as previous report in which Lin28A and Lin28B is reversely expressed in breast cancer." (PMID 27793004, 2016). "In summary, we show that Lin28A plays an important activating role in the AR expression via c-myc and thereby promotes ER-/Her2+ breast cancer cell prolification and invasiveness." (PMID 27494865, 2016). "Recently, it was also found that LIN28A/LIN28B promotes the expression of human epidermal growth factor receptor 2 (HER2) at the post-transcriptional level in breast cancer cells." (PMID 26123544, 2015).
breast carcinoma (continued). "Similarly, STAT3 directly stimulates Lin28A/B expression by binding to its promoter in breast cancer cells." (PMID 36230562, 2022). "This suggests that lin28A could be involved in the regulation of MZF1 expression via let-7 in breast cancer." (PMID 29396433, 2018). "In Du145 cells, the overexpression of HAPTOV1 also associated to significantly increased levels of stemness genes LIN28A, ALDH1A1 and MYC, whereas in PC3 cells it associated to a significant expression of LIN28A, MYC, NANOG and POU5F1 genes, in agreement with reports in breast cancer cells." (PMID 28938627, 2017). "Our results indicate that, if feasible strategies to reconstitute Lin28A in breast tumors can be developed, reconstitution of Lin28A may become a potential therapeutic agent for breast cancer treatment." (PMID 27494865, 2016). "Our data showed that Lin28A can induced AR expression in ER−/Her2+ breast cancer cells." (PMID 27494865, 2016). "Having previously demonstrated the co-expression status of the Lin28A and androgen receptor (AR) in ER−/Her2+ breast cancer, we tested the hypothesis that Lin28A can activate AR and promotes growth of ER−/Her2+ breast cancer." (PMID 27494865, 2016). "Our results suggest that the expression of Lin28A may be an attractive target for therapeutic intervention by enhancing AR in ER-/Her2+ breast cancer." (PMID 27494865, 2016). "Further studies are required to elucidate the roles of Lin28A and AR network in breast cancers." (PMID 27494865, 2016). "Having previously demonstrated the co-expression status of Lin28A and androgen receptor (AR) in ER−/Her2+ breast cancer, this study showed that Lin28A can induce the expression of AR via regulation of c-myc in ER−/Her2+ breast cancer." (PMID 27494865, 2016). "Based on these results, we speculated that Lin28A induces invasion of ER-/Her2+ breast cancer cells through basement membrane in vitro." (PMID 27494865, 2016). "In addition, a positive correlation was found between the expression of Lin28A and AR in the tumors of ER-/Her2+ breast cancer xenograft models, indicating that a positive feedback loop exists between Lin28A and AR." (PMID 27494865, 2016). "Lin28A may regulate expression of prosurvival genes in ER-/Her2+ breast cancer via one of these mechanisms." (PMID 27494865, 2016). "Because Lin28 represses let-7 expression, we speculated that Lin28a might mediate the stemness of breast cancer via downregulation of let-7." (PMID 24349438, 2013). "Overexpression of Lin28A and Lin28B is associated with poor prognosis in various cancers, such as oral squamous cell carcinoma (OSCC), colon cancer, epithelial ovarian carcinoma (EOC), gastric cancer, hepatocellular carcinoma (HCC), breast cancer, esophagus cancer, and other malignancies." (PMID 30976203, 2019). "In vertebrates there are two LIN28 paralogs, LIN28A and LIN28B, which are aberrantly expressed in numerous human cancers, including T-cell lymphoma, neuroblastoma, breast cancer, and hepatoblastoma." (PMID 38612395, 2024). "Here, we uncover its mechanistic significance by characterizing a novel resistin/LIN28A/Let-7a/IL-6/STAT3 signaling axis supporting the growth and stemness of breast cancer cells." (PMID 34572725, 2021). "In breast cancer cells, depletion of C-MYC by siRNA decreased LIN28A transcript and protein level, whereas overexpression of C-MYC restored LIN28A expression." (PMID 28400788, 2017). "LIN28A was also found to activate the translation of human epidermal growth factor receptor 2 (HER2) and HMGA1 by directly interacting with their mRNA in breast cancer cells." (PMID 28400788, 2017). "Another study provided some intriguing results on the role of LIN28A in the epithelial-to-mesenchymal transition (EMT), an important characteristic of CSCs, and stemness in breast cancer cells." (PMID 28400788, 2017).
breast carcinoma (continued). "Many studies have shown that LIN28A/LIN28B promotes and let-7 inhibits invasion and metastasis in various cancer types, including colon cancer, breast cancer, hepatocellular carcinoma, pancreatic cancer, gastric cancer, lung cancer and esophageal cancer." (PMID 26123544, 2015). "Increased Lin28A expression remarkably increases E-cadherin but reduces Vimentin expression and, subsequently, increases the epithelial CSC marker ALDH activity and colony formation via the downregulation of let-7a in breast cancer." (PMID 34572067, 2021). "Specifically in 33 breast cancer tumors that we interrogated by immunohistochemistry, 9 were LIN28A+, 10 were LIN28B+, and none were positive for expression of both genes." (PMID 28400788, 2017). "The expression levels of Lin28A and Lin28B in tumor tissues were higher than those in normal breast tissues, the Lin28A expression in HER2-Enriched breast cancer was slightly higher than other sub-type breast cancers, and the Lin28B expression was significantly higher in basal-like breast cancer." (PMID 31754343, 2019). "Thus, we utilized the mRNA expression array data from TCGA to investigate the correlation between MZF1 and lin28A and lin28B mRNA (LIN28A and LIN28B) in breast cancer and found that MZF1 expression correlates positively with the expression of lin28A, but not lin28B." (PMID 29396433, 2018). "However, a substantial proportion of breast cancer patients do not respond to this drug, Targeting Her-2 alone by trastuzumab may, under some conditions, not be sufficient to halt the rapid growth of tumor cells that also express high levels of Lin28A." (PMID 27494865, 2016).
ovarian carcinoma (20 papers, 2012 to 2025). A malignant neoplasm originating from the surface ovarian epithelium. "In our previous studies, it was found that Lin28A high expression altogether with co-expression of Oct4 is associated with poor prognosis of ovarian cancer, while the roles and its mechanism on the development of OC remains unknown." (PMID 30266988, 2019). "LIN28, a highly conserved RBP, has two homologues LIN28A/B in mammals and expressed in various human epithelial tumors, such as lung cancer, ovarian cancer, hepatocellular carcinoma, and colorectal cancer." (PMID 36059653, 2022). "HSBP1 is a 76-amino-acid protein that binds to heat shock factor 1(HSF1), which can be enhanced through lin28A to regulate the stem-like characteristics of ovarian cancer." (PMID 36276091, 2022). "Tumor‐suppressive actions of let‐7 are attributed to its role in suppressing oncogenes and genes involved in maintenance of pluripotency, such as HMGA2 and LIN28A, and let‐7 directly targets these genes in ovarian cancer." (PMID 32652647, 2020). "Two ovarian cancer cell lines, A2780 with relatively low level of Lin28A and PA-1 with high level of endogenous Lin28A expression, respectively, were chosen for our study." (PMID 30266988, 2019). "A recent study showed that LIN28A binds to bone morphogenetic proteins 4 (BMP4) mRNA promoting its expression at a post-transcriptional level in ovarian cancer cells." (PMID 28400788, 2017). "Intriguingly, TTP was shown to increase levels of mature let-7a, let-7b, let-7f, and let-7g miRNA by post-transcriptionally inhibiting LIN28A expression in ovarian cancer cells." (PMID 28400788, 2017). "Second, the role of Lin28A in regulating HSBP1 could be specific to ovarian cancer due to its involvement in maintaining stemness characteristics, which are more pronounced in ovarian cancer stem cells." (PMID 39150660, 2025). "In this study, we further confirmed that Lin28A can up-regulate the protein expression of RAN/HSBP1 to promote the stemness, the proliferation, the invasion and to inhibit the apoptosis of ovarian cancer cells." (PMID 32398961, 2020). "Then we detected the expression of Lin28A, RAN and HSBP1 in 47 ovarian benign tumor tissues and 96 ovarian malignant tumor tissues by immunohistochemical analysis." (PMID 32398961, 2020). "Taken together, data presented here demonstrate that high LIN28A expressing ovarian cancer cells secrete exosomes that, when taken up by nonmetastatic target cells, induce EMT-related gene expression and invasion and migration." (PMID 26583126, 2015).
hepatocellular carcinoma (18 papers, 2012 to 2025). A malignant tumor that arises from hepatocytes. "Our finding is consistent with our report that HBx was able to activate Sp1 in up-regulation of Lin28A/Lin28B in hepatoma cells." (PMID 27050367, 2016). "Interestingly, we have reported that HBx activates Lin28A/Lin28B through Sp1/c-Myc in hepatoma cells." (PMID 27050367, 2016). "We previously reported that HBx activated Lin28A/Lin28B through Sp1/c-Myc in hepatoma cells." (PMID 27050367, 2016). "Lin28A was first discovered in nematode Caenorhabditis elegans, and was proved to regulate the developmental timing, whereas Lin28B was first discovered in hepatocellular carcinoma(HCC), where it is highly expressed." (PMID 27793004, 2016). "LIN28A was originally identified in Caenorhabditis elegans as a heterochronic gene and shown to affect embryonic developmental timing, whereas LIN28B was first identified in hepatocellular carcinoma (HCC)." (PMID 40265419, 2025). "It has been reported that the LIN28A and LIN28B genes are reactivated in many human malignancies, such as breast cancer, colon cancer, lung cancer, ovarian cancer and hepatocellular carcinoma (HCC), and their expression is correlated with poor clinical disease outcomes." (PMID 34548635, 2022).
lung carcinoma (15 papers, 2012 to 2024). "In accordance with these reports, we found that miR-98 overexpression caused LIN28A downregulation and blocked lung cancer cell migration/invasion and metastasis." (PMID 28587210, 2017). "To determine whether the downregulation of MMP2/9 caused by loss of LIN28A influenced lung cancer cell metastasis, we carried out migration and invasion assays in A549 cells transfected with LIN28A siRNA." (PMID 28587210, 2017). "In the previous study, curcumin could enhance miR-98 level to inhibit LIN28A mRNA level, resulting in suppressing lung cancer cell growth and invasion." (PMID 35585935, 2022). "To further confirm the Fhit-dependent miR-20a/b regulation, we analyzed the endogenous expression of both Lin28A and Lin28B expression, and found that Lin28B is abundant in A549 and H1299 lung cancer cells and HEK293 cell compared to HCT116 colorectal cancer cell." (PMID 33437205, 2021). "In this study, we found that curcumin stimulates the expression of miR-98, which in turn negatively regulates LIN28A-induced lung cancer invasion and migration may through inhibition MMP2 and MMP9." (PMID 28587210, 2017). "LIN28A knockdown suppressed both migration and invasion, indicating that curcumin inhibits MMP2/9 expression via suppression of LIN28A in lung cancer cells." (PMID 28587210, 2017). "We have also identified additional regulators such as LIN28A and CPEBP4 that were not previously studied in the context of lung cancer." (PMID 27186987, 2016).